INS (insulin)
Diseases named in the same sentence as INS in open-access papers (continued):
Sharing a sentence is not in itself a finding about the gene and the disease.
Nephropathy (continued). "They suffered from severe renal disease, had less endogenous insulin and were frequent users of sulfonylureas." (PMID 30835778, 2019). "The patient’s alcohol consumption, nephropathy, neuropathy, previous cataract surgery, severity of diabetic retinopathy, and insulin usage were statistically significant factors with regard to the DME prevalence." (PMID 29649995, 2018). "Low insulin sensitivity (as measured by the minimal model technique) has been described in people with renal disease but a normal eGFR (evaluated by inulin clearance); insulin sensitivity was similar across the range of eGFR." (PMID 29855339, 2018). "In our pilot study we found that in patients with a principal diagnosis of DM, most required insulin, roughly two-thirds had renal disease and almost a third had very poorly controlled diabetes with an A1C > 10%." (PMID 28702257, 2017). "In contrast, patients receiving bypass surgery were more likely to have retinopathy, nephropathy, and chronic renal disease, and insulin therapy." (PMID 27857178, 2016). "Patients who were treated with insulin alone were significantly younger but exhibited more advanced kidney disease with a lower eGFR and higher UACR." (PMID 27286816, 2016). "At baseline, 28% of patients in the insulin monotherapy group had a prior history of renal disease versus 18% in the insulin plus metformin group." (PMID 27152598, 2016). "Insulin use, presence of nephropathy, and age ≥45 years have demonstrated a significant increased risk with OR more than 2 in all affected, foot ulcer, gangrene, and amputation cases." (PMID 25946144, 2015). "The proportions of patients with renal disease during follow-up in insulin, EBID and EBID + insulin groups were 14.2%, 4.7% and 6.5%, respectively." (PMID 25616979, 2015). "Overall, 4% (n = 1576) of patients had evidence of renal disease before initiation of EBID or insulin." (PMID 25616979, 2015). "Betulinic acid and oleanolic acid, both pentacyclic triterpenoids, have shown multiple biological activities with apparent effects on glucose absorption, glucose uptake, insulin secretion, diabetic vascular dysfunction, retinopathy and nephropathy." (PMID 25396726, 2014). "Patients with higher levels of A1C also showed a significantly higher prevalence of nephropathy and were more frequently on insulin treatment." (PMID 24358222, 2013). ""“...so they (patients) feel that the moment they put insulin, after a few years is kidney damage, then dialysis." (PMID 22469132, 2012). "The samples can subsequently be analyzed for insulin, C-peptide, and other markers along with confirmatory laboratory glucose measurement and routine blood samples for renal disease, liver disease, and sepsis." (PMID 22768352, 2012). "Intensive insulin therapy and protein restriction delay the development of nephropathy in a variety of conditions, but few interventions are known to reverse nephropathy." (PMID 21533091, 2011). "These patients face life-long risks for blindness, cardiovascular and renal diseases, and complications of insulin treatment." (PMID 20949090, 2010). "On the other hand, clinical research indicates that in kidney disease the concentration is increased despite the simultaneous reduction in insulin sensitivity." (PMID 19804653, 2009). "Apelin, a regulator of insulin sensitivity, has demonstrated protective effects in diabetic retinopathy, while galectin-3 has been identified as a key factor in fibrosis and inflammatory responses, particularly in nephropathy and neuropathy." (PMID 40137149, 2025). "Similarly, those identified within the Combined Insulin-Resistant and Deficient Diabetes (CIRDD) group are followed up rigorously with more stringent surveillance for retinopathy and nephropathy." (PMID 40763148, 2025).
Nephropathy (continued). "In the mild nephropathy group, factors that were significantly associated with PDR compared to mild retinopathy included systolic (p=0.044) and diastolic blood pressure (p=0.009), urine albumin/CR (p=0.034), HbA1c (p=0.0094), and insulin use (p=0.0048)." (PMID 40822949, 2025). "The condition arises from the inability of peripheral tissues to respond to insulin and insufficient insulin production by pancreatic β-cells, leading to high blood sugar and serious complications such as heart disease, neuropathy, retinopathy, and kidney disease." (PMID 40807540, 2025). "Epidemiological studies have revealed links between exposure to certain PFAS and various health issues, including impaired immune and thyroid function, liver disease, lipid and insulin imbalances, kidney disease, adverse reproductive and developmental outcomes, and cancer." (PMID 41008586, 2025). "This indicates that the intervention may improve glucose metabolism and insulin sensitivity, which are crucial factors in managing diabetic complications such as cardiovascular disease and nephropathy." (PMID 38494538, 2024). "Most patients (98.5%) used insulin injections, and 79.7% underwent nephropathy screening." (PMID 39539431, 2024). "Our nephropathy findings could be interpreted by having more controlled patients among the non-insulin-managed group since the average HbA1C reduction among diabetic patients with HbA1C of 9 % or more was significantly different between the two groups." (PMID 39295783, 2024). "Hence, the variation of insulin kinetics in patients with CKD, in addition to the complications of the renal disease itself, is regarded as a challenge to practitioners when determining the appropriate insulin dosing." (PMID 39850482, 2024). "The lack of detailed characterization of the diabetic subjects such changes in HbA1c levels, fasting and postprandial blood glucose levels, insulin sensitivity, insulin resistance, beta-cell function, and diabetic complications such as retinopathy, neuropathy, and nephropathy." (PMID 37627295, 2023). "This indicates that, by improving insulin concentration and enhancing insulin sensitivity with Obex®, we are helping to decrease hyperuricaemia, which affects creatinine concentration, thereby helping to prevent early kidney damage." (PMID 36804035, 2023). "These cardiovascular risk factors contribute to kidney damage through various mechanisms, including increased insulin resistance, inflammation, oxidative stress and renin-angiotensin-aldosterone system activation, which in turn can promote the development of kidney damage in young adults." (PMID 37055746, 2023). "The model achieved good discrimination and calibration by using highly accessible predictors collected in routine clinical settings, including age, sex, heart failure, cerebrovascular disease, moderate or severe kidney disease, moderate or severe liver disease, cancer, insulin use, HbA1c, and HDL‐C." (PMID 36526273, 2023). "Conversely, several studies have reported that inhibition of CD38 may lead to the exacerbation of the pathological conditions such as insulin secretion, and cardiovascular and kidney disease." (PMID 36831262, 2023). "The final prediction model included age, sex, heart failure, cerebrovascular disease, moderate or severe kidney disease, moderate or severe liver disease, cancer, insulin use, HbA1c, and HDL‐C, which balanced the predictive validity and parsimony of the model well." (PMID 36526273, 2023). "Furthermore, surgical removal of visceral fat in rats was proved to be beneficial for improving insulin sensitivity, reducing the incidence of liver and kidney disease, and extending lifespan." (PMID 36814582, 2023). "The metabolic variables and pathological examination demonstrated that Leprdb/db mice significantly enhanced body weight (approximately 1.8-fold vs. Leprdb/m mice), elevated glucose, insulin, and triacylglycerol, and exacerbated retinopathy and nephropathy compared with Leprdb/m mice." (PMID 36406423, 2022).
Nephropathy (continued). "All these results suggest that HPE protects against nephropathy via insulin sensitivity regulation." (PMID 35885378, 2022). "Interestingly, nephropathy was primarily seen in the insulin-resistant subgroup of SIRD in the new classification of T2D." (PMID 35948367, 2022). "Nevertheless, modulation of Cdc42 activity and its regulatory pathways might serve as a therapeutic target to prevent a vicious cycle in which kidney damage and impaired insulin secretion interact with each other and ultimately lead to an aggravated outcome." (PMID 36034435, 2022). "Elderly diabetic patients are likely to develop decreased insulin sensitivity due to sarcopenia, and it is necessary to pay attention to the intake of zinc-containing foods when providing nutritional guidance to diabetic patients with nephropathy." (PMID 36539708, 2022). "Alternatively, alterations in diet, gut microbiota, or insulin sensitivity that accompany kidney disease may impact the metabolome." (PMID 36048534, 2022). "Emerging evidence points to potentially important roles of HDL-ApoM-S1P in heart failure and kidney disease, and it will be of interest to examine whether this complex links insulin action to those pathologies." (PMID 35104242, 2022). "Although insulin injection effectively controls blood glucose levels, it cannot recapitulate the physiological pancreatic insulin secretion pattern and thus may result in complications such as neuropathy, nephropathy, retinopathy, and heart disease." (PMID 34513805, 2021). "After 12 weeks, diabetic rats developed nephropathy as proven by metabolic alterations (increased blood glucose, insulin, HOMA-IR, triglycerides, cholesterol) and renal abnormalities (podocyte injury, microalbuminuria, increased serum creatinine, decreased creatinine clearance)." (PMID 34439892, 2021). "Therefore, it is necessary to take measures to reduce the blood insulin concentration in the IGT stage to prevent IGT nephropathy." (PMID 33967958, 2021). "The described approach will allow to study insulin secretion also in other metabolic disorders possibly affecting C-peptide kinetics (e.g., renal diseases) or to study secretion of other hormones for which a population model of the kinetics is not yet available (e.g., glucagon)." (PMID 33790855, 2021). "If insulin sensitivity is improved, the possibility of developing nephropathy can be reduced." (PMID 32604723, 2020). "The burden of comorbidities including cancer and renal disease was largest in the insulin group." (PMID 32631337, 2020). "DCDC2 in the context of kidney diseases is linked to renal ciliopathies and nephronophthisis; however, insulin signalling is not directly linked to these disorders." (PMID 33458251, 2020). "The ideal T2DM patient scheduled for SPK is lean, insulin dependent and suffers from renal disease." (PMID 32106853, 2020). "These included limited information relating to the reason for test referral, ethnicity, socioeconomic status, and co-morbidities; especially those surrounding hepatic and renal disease, which could impact insulin and/or c-peptide clearance." (PMID 32375229, 2020). "In patients on multiple medications and/or insulin or who have multiple dietary restrictions or other co-morbidities such as renal disease, low-carbohydrate diets should be supported by experienced health care professionals and a specialist dietitian who can facilitate optimal nutritional intake." (PMID 32276484, 2020). "Clinical hypoglycemic events may occur from insulin overdose, hepatic or renal disease, chronic alcoholism, or in cases of hypoglycorrhachia associated with infections." (PMID 32214088, 2020). "Decreased muscle mitochondrial respiratory capacity has indeed been reported in patients with CKD and in models of kidney disease, but has not been linked directly to insulin resistance." (PMID 31195596, 2019).
Nephropathy (continued). "In addition, the protective effects of apelin has been reported in metabolic diseases where it decreased adiposity, serum insulin and increased insulin sensitivity; and in renal diseases where it decreased acute renal injury and fibrosis." (PMID 31882594, 2019). "In addition, treatment regimen distress was associated with having been divorced (p < 0.0001), employed (p = 0.001), smoker (p = 0.007), insulin and oral hypoglycemic drugs users (p = 0.03), peripheral vascular disease (p = 0.018), and nephropathy (p = 0.015)." (PMID 29770340, 2018). "Besides its antidiabetic effect, dapagliflozin has also been found to prevent the development of nephropathy, probably by decreasing body weight, uric acid, blood pressure, lipid metabolism, inflammation and improving insulin resistance." (PMID 29301371, 2018). "Low insulin adherence leads to poor glycemic control and may exacerbate microvascular and macrovascular complications such as kidney disease, dyslipidemia, stroke, retinopathy, nephropathy, and neuropathy and may increase episodes of hypoglycemia." (PMID 29520741, 2018). "This is probably due to decreased insulin secretion in people with kidney disorders which might be due to metabolic acidosis, increased parathyroid hormone and decreased vitamin D level." (PMID 28497087, 2017). "Insulin requirements show a biphasic course in diabetic patients with advanced renal disease." (PMID 27513562, 2016). "Vitamin E may help reduce the risks of retinopathy and nephropathy, selenium supports insulin signalling and wound healing but may be harmful in excess, and vitamin C contributes to glycemic control, immunity, and wound healing, though findings require further validation." (PMID 41280964, 2025). "Intriguingly, genetic ablation of Nedd4-2 in this diabetic model did not exacerbate kidney disease severity beyond Nedd4-2 loss alone, but corrected metabolic parameters via a reduction of aldosterone levels, restoration of insulin signaling and reduced blood glucose levels." (PMID 40617804, 2025). "Therefore, we conducted this retrospective study to analyze the insulin dose characteristics of T2DKD patients undergoing short-term CSII therapy in different stages of renal disease and to analyze the impact of combined oral hypoglycemic drugs on insulin dosage during CSII therapy." (PMID 40114703, 2025). "In PTx, the vascularized transplanted organ rapidly restores endogenous insulin production, resulting in a substantial improvement in glycemic control, sustained insulin independence over years and the potential for regression of diabetic degenerative complications, including nephropathy lesions." (PMID 38213551, 2023). "In addition, malignancy, insulin use, and the presence of pre-existing liver or renal disease might be other contributing factors for hospitalization at older ages." (PMID 37149604, 2023). "Although insulin is filtered through the glomerulus, it is almost completely reabsorbed in the renal tubules, so the existence of insulin in the urine in people with abnormal reabsorption due to kidney damage could be misinterpreted as an insulin overdose." (PMID 35324747, 2022). "Moreover, rats with insulin treatment had significant lower serum urea nitrogen, serum uric acid, and serum creatinine than DKD rats, indicating that STZ-induced kidney damage was associated with pancreatic β-cell damage." (PMID 35696643, 2022). "The insulin deficit leads to high levels of blood glucose (HG), which, if not tightly controlled, leads to disabling and life-threatening health complications including cardiovascular diseases, retinopathy, neuropathy, nephropathy, and prolonged/incomplete wound healing." (PMID 32660119, 2020). "However, with regard to improvement of metabolic conditions SPK might still be a considerable treatment option for lean insulin dependent type 2 diabetics suffering from renal disease." (PMID 32106853, 2020).
Nephropathy (continued). "Disruption in insulin regulation and resistance leads to increased formation and accumulation of advanced end products (AGEs), which further enhance oxidative and nitrosative stress leading to microvascular (retinopathy, neuropathy, and nephropathy) and macrovascular complications." (PMID 30046616, 2018). "Nephropathy could influence insulin doses by decreasing its renal excretion." (PMID 27011769, 2016). "Consistent with more severe nephropathy, TRAIL-/-ApoE-/- mice had reduced appetite and were eating less than ApoE-/- mice within the last 4 w of the study; supported by the markedly reduced plasma glucose levels at 20 w, even though TRAIL-deficient mice were still insulin resistant." (PMID 24667560, 2014). "We excluded individuals with a history of lipid-lowering, antihypertensive, insulin, or hormone replacement therapy (HRT) medications, as well as those with kidney disease, to ensure the accuracy of our analysis." (PMID 39765929, 2024). "Age, sex, BMI, smoking, time since diagnosis, insulin treatment, values of HbA1c, SBP, HDL-cholesterol and triglycerides, presence of retinopathy, nephropathy, neuropathy and CVDs." (PMID 37485272, 2023). "However, the insulin group had a significantly longer duration of DM (p < 0.001), more severe grade of DR (p = 0.028), poorer DM control (p = 0.033), a higher proportion of hypertensive patients (p = 0.014), and a greater proportion of nephropathy (p = 0.002) compared to the OHA group." (PMID 35227220, 2022). "SIRT1 is responsible to regulate insulin secretion, insulin resistance, lipid/glucose/energy metabolism, inflammatory process, CVD, and kidney diseases." (PMID 35317114, 2021). "The great majority of respondents did not know whether metformin could cause kidney damage (n = 2651, 82.6%) and more than half did not know whether long-term drug use could cause organ failure (n = 2073, 64.6%) and whether insulin could cause harmful effects (n = 1836, 57.2%)." (PMID 32064183, 2020). "In this study, 48.3, 27.3, 14.9 and 58% of patients receiving insulin were having CVD, retinopathy, nephropathy and neuropathy, respectively compared to 29, 12.5, 4.4 and 22.8% in patients using OHA (p < 0.001)." (PMID 29483946, 2018). "However, nephropathy was significantly more prevalent in the group treated by diet alone than in those receiving any type of hypoglycemic medication (p < 0.001; χ2 = 51.4), and neuropathy was more prevalent in patients receiving insulin or oral hypoglycemic treatments (p = 0.008; χ2 = 9.6)." (PMID 26109389, 2015). "These include regulating glycolipid metabolism, suppressing inflammation (↓TNF-α/IL-6), improving insulin sensitivity (↓HOMA-IR), and enhancing vascular function (↑NO/FMD), while concurrently alleviating complications such as retinopathy, nephropathy, and sexual dysfunction." (PMID 41001671, 2025). "In each group of kidney disease, TDD, TDD kg−1, and total basal insulin dose per kilogram (TBa kg−1) at the time of achieving blood glucose target showed a downward trend with the decrease of eGFR, and the overall comparison differences were statistically significant." (PMID 40114703, 2025). "Taken with our results, this suggests a local upregulation of CTSS expression (which may be driven by insulin resistance) occurs in the glomeruli and tubules in DKD which may contribute towards kidney damage." (PMID 39562547, 2024). "Various complications such as angiopathy, nephropathy, retinopathy, neuropathy, inflammation, etc., characteristic of the diabetic state may in fact result from RAS dysregulation against insulin dysfunction due to pathology and/or medication." (PMID 38323106, 2024). "Although vitamin E does not have an insulin sensitivity-enhancing feature, research results are indicating that it can be a protective agent against the formation of DM-related nephropathy due to its intense anti-oxidant property." (PMID 37009001, 2023).